ABO (ABO, alpha 1-3-N-acetylgalactosaminyltransferase and alpha 1-3-galactosyltransferase)
Diseases named in the same sentence as ABO in open-access papers (continued):
Sharing a sentence is not in itself a finding about the gene and the disease.
infection (continued). "This text reviewed association studies published in recent decades focusing on the potential contribution of the ABO, Lewis, and Secretor histo-blood group carbohydrates and infection by T. gondii." (PMID 34222043, 2021). "In the light of these observations, the biological role of ABO, Lewis, and Secretor histo-blood group carbohydrates in the infection by T. gondii remains unsolved and requires new strategies for investigations." (PMID 34222043, 2021). "We compared infection prevalence with linear regression, using reference groups O for ABO and Rh-positive for Rh(D), and using bootstrap to compute 95% confidence intervals for each estimate." (PMID 32511586, 2020). "No such significant associations were obtained between both all stage and mature gametocyte stage positivity and the ABO blood type (A, B, 0 and AB) or infection density." (PMID 31022294, 2019). "The model included the composite risk score, along with age, sex, sex matching, height, weight, diagnosis, HLA ratio, granulocyte engraftment time, megakaryocyte engraftment time, hematopoietic recovery time, donor source, ABO mismatch, and Infection with bacteria, viruses, or fungi." (PMID 41607786, 2026). "The presence of this mutation in individuals with blood group A supports the hypothesis that host-specific ABO antigens may influence infection dynamics and disease progression." (PMID 40872268, 2025). "Similarly to the ABO system, data regarding the role of Rh blood type in the host response to infection are inconsistent." (PMID 41303137, 2025). "The most pronounced association between ABO blood group incongruence and infant infection was at 90 days from birth but not at 30 days, the time when passively transferred antibodies from mother to newborn were at the highest level." (PMID 39476233, 2024). "It is known that a different ABO frequency can affect the likelihood of infection." (PMID 35683418, 2022). "As the results of this meta-analysis appear to highlight a protective role of anti-A isoagglutinin against SARS-CoV-2 infection, there is a clear need for titration of isoagglutinin ABO for a better understanding of the role of the blood groups in the infection." (PMID 35683418, 2022). "The result found that ABO and HLA incompatibilities could increase the probability of infection-medicated rejection and influence the overall survival both for patient and graft." (PMID 34389032, 2021). "In these conditions, the impact of ABO phenotypes on furin could take place both at the infection level and at the late stage of severe disease." (PMID 33499228, 2021). "Better understanding these characteristics of histo-blood group carbohydrates may improve understanding of how ABO, Lewis, and Secretor contribute to infection by T. gondii." (PMID 34222043, 2021). "Overall (meaning that we do not consider the ABO blood group), Rh-negative pregnant patients at term (OR = 1.22), compared with Rh-positive patients (OR = 1), are at higher risk for infection with SARS-CoV-2, but this is not statistically significant." (PMID 34069202, 2021). "Looking at a more homogeneous group of countries, both in terms of ABO coefficient of variation and of socioeconomic status, European countries also show a clear relationship between the distribution of ABO blood groups and infection attack rates (r2 = 0.29, p = 0.012)." (PMID 33499228, 2021). "The virus spike (S) protein binding to the specific ABO glycan antigen receptors may support virus entry during infection." (PMID 33401440, 2021). "But for the Botswana population, the ABO groups do not appear to have any role in enhancing or diminishing HIV risk of infection." (PMID 26900853, 2016). "For example, Arendrup and colleagues reported that HIV from lymphocytes of blood group A individuals was neutralized by anti-A, implying that this mechanism could potentially reduce the likelihood of infection in ABO discordant couples." (PMID 26900853, 2016).
infection (continued). "The information collected included: diagnosis of ABE at hospital presentation; general characteristics such as place of birth, source of referral, and sex; and a selection of suspected causes of jaundice including prematurity, infection, G6PD status, ABO and Rh incompatibility." (PMID 27057339, 2015). "Although the state is hyper-endemic to P. falciparum malaria and contributes 29.8% of deaths related to the infection, no study has been carried out in the local population to assess the association of ABO blood group in severe infection." (PMID 22011404, 2011). "Likewise, analysis of outbreaks showed a strong impact of either the secretor or the ABO phenotypes on infection." (PMID 21901093, 2011). "Anti-ABO antibodies could also help controlling infection by other coronaviruses as these viruses are highly glycosylated and replicate in epithelial cells of the upper respiratory tract that strongly express ABH antigens in accordance with the ABO and FUT2 genes polymorphisms." (PMID 33499228, 2021). "This implied that the expression of ABO antigens on mucosal surfaces could influence infection." (PMID 32244465, 2020). "Therefore, SARS-CoV-2 harboring ABO antigens could be possibly neutralized by the anti-A or anti-B antibodies, both being present in O-group individuals, which could bring some protective role against infection and replication." (PMID 34967260, 2022). "Analysis of the whole data set demonstrated that the distribution of the ABO blood groups among the patients, independent of infection by H. pylori, followed the same proportions as the blood groups found in the general Brazilian population." (PMID 11994774, 2002). "This implies that the encoded protein, Histo-blood group ABO system transferase (BGAT), may somehow contribute to a higher susceptibility of infection but not a poorer prognosis." (PMID 35970849, 2022). "Previous studies like the one leaded by “The COVID19 Host Genetics Initiative” support the notion that some genetic variants, most notably at the ABO and PPP1R15A loci, in addition to SLC6A20 have a direct effect on susceptibility to infection rather than COVID19 severity." (PMID 35937703, 2022). "A higher susceptibility to SARS-CoV-2 infection because of individually pre-existing low ABO antibody levels facilitating virus attachment to host cells, rather than other dynamic changes in response to the infection, may be suggested." (PMID 35956128, 2022). "These authors again suggested a role for the ABO antigens in the immune response and proposed that ABO antigens may be more important in the progression of the disease rather than in initial infection." (PMID 32244465, 2020). "Thus, the possibility that anti-ABO antibodies could play a role in protecting from infection and reducing the viral load is valuable and should not be overlooked." (PMID 34972836, 2021). "Of note, the time between initiation of ABO-IA and the recovery from PRCA was short, and no cases of GVHD or infection occurred during the treatment phase or the follow-up period of 3 months after the last treatment." (PMID 33195341, 2020).
cancer (73 papers, 2009 to 2025). A tumor composed of atypical neoplastic, often pleomorphic cells that invade other tissues. "It has long been established that the urothelium glycome undergoes significant remodeling during cancer progression, with early studies linking the loss of ABO blood group determinants in secretor individuals to poorer prognosis." (PMID 40430030, 2025). "The relationship between genetic variants of the ABO locus and the mechanism by which the ABO blood group is at interplay with cancer development and progression remains an open question." (PMID 39132152, 2024). "Despite a multitude of studies attempting to correlate the ABO phenotype with cancer risk, the link between the expression of histoblood group antigens and tumorigenesis has remained unclear for most evaluated tumor types." (PMID 39040623, 2024). "ABO gene polymorphism has been implicated in susceptibility to several cancers across different populations." (PMID 39132152, 2024). "Evidence of an association between ABO blood group antigens and various types of cancers has been investigated by several studies 17-23." (PMID 39132152, 2024). "The role of inherited blood group antigens in cancer risk and progression has been examined for many types of solid organ tumors, but few studies assessed how the ABO blood group impacts the survival of patients with HCC." (PMID 37296868, 2023). "We found the ABO/RhD blood groups to be associated with a wide spectrum of diseases including cancers and musculoskeletal-, genitourinary-, endocrinal-, infectious-, cardiovascular-, and gastrointestinal diseases." (PMID 36892462, 2023). "Over the last decade, many clinical studies have been conducted to investigate the association between certain types of cancer and the ABO and Rh blood groups." (PMID 38013340, 2023). "Numerous research studies have investigated the relationship between ABO and Rhesus (Rh) blood groups and the risk of various cancers, yielding diverse findings." (PMID 38013340, 2023). "Among the genetic loci identified in this study, rs4072037 (MUC1) and rs1053878 (ABO) have been reported to be associated with the occurrence and development of cancers." (PMID 35144566, 2022). "It has been recently discovered that the existence of ABO antigens on the surface of cancer cells, although different from normal cell ABO antigens, is still associated with the ability of these cells to escape an immune system reaction, escaping apoptosis." (PMID 35323176, 2022). "Further studies on cancer and prothrombotic genotypes point out that VTE risk increased by 11–12-fold as a result of the simultaneous presence of cancer and rs8176719 (ABO) risk variant." (PMID 34765649, 2021). "Despite the multitude of studies attempting to correlate ABO phenotype with cancer risk, the link between expression of histoblood group antigens and tumorigenesis and the mechanism of action was unclear for most tumor types evaluated." (PMID 34376742, 2021). "In this study, we conducted a systematic review and meta-analysis to clarify the association between two SNPs (rs505922 and rs657152) in ABO gene and cancers/cardiocerebrovascular diseases." (PMID 32093636, 2020). "In this study, we conducted a meta-analysis to clarify the relationship between ABO SNPs (rs505922 and rs657152) and cancer/cardiocerebrovascular diseases risk." (PMID 32093636, 2020). "Here, we have performed a meta-analysis including the newly published studies and evaluated the associations between polymorphisms of ABO gene and cancers/cardiocerebrovascular diseases." (PMID 32093636, 2020). "Several SNPs in the ABO gene have been suggested to be associated with increased risks to the development of cancer and cardiocerebrovascluar disease by genome-wide association studies (GWAS) and candidate gene studies." (PMID 32093636, 2020).
cancer (continued). "Some studies have suggested the relationship between the ABO blood type and the risk of various carcinomas, including colorectal cancer, renal cell carcinoma, and pancreatic carcinoma 8-10." (PMID 31777605, 2019). "ABO antigen type has been postulated from many reports as a risk factor for some cardiovascular diseases, cancers, and infectious diseases." (PMID 29780641, 2018). "Most of previous prospective studies only examined the ABO blood type with risk of single cancer site." (PMID 28880901, 2017). "The associations between ABO blood type and risk of all cancer and specific cancers were examined in a prospective cohort study of 18,244 Chinese men enrolled in 1986." (PMID 28880901, 2017). "Many reports have shown that the ABO blood type system is associated with the development of cancers." (PMID 26940066, 2016). "Despite the multitude of studies attempting to correlate ABO phenotype with cancer risk, the link between expression of histoblood group antigens and tumorigenesis was unclear for most tumor types evaluated." (PMID 28031957, 2016). "Although associations between blood group and cancer risk have been evaluated at the phenotype (antigen expression) and genotype (SNPs in ABO) levels, expression of blood group antigens can be modified by other genes." (PMID 28031957, 2016). "Several plausible mechanisms, such as inflammation, immune-surveillance of malignant cells, and membrane signaling, have been proposed to explain this observed association between the ABO blood group and cancer risk." (PMID 27733208, 2016). "Another interesting field that has been extensively studied over the past five decades is that of the association between ABO blood group types and cancer." (PMID 25592962, 2015). "Loss of blood group antigen A/B expression on cancer cells is regulated by hypermethylation of the ABO gene promoter, which is an early event in tumor development." (PMID 26411553, 2015). "Recently, the association between the ABO blood type and survival of cancer patients has drawn much attention." (PMID 26411553, 2015). "Many previous studies have reported an association between ABO blood group and the risk of various cancers, especially epithelial cancers." (PMID 20694147, 2010). "Prior investigations have established the ABO antigen as a cancer-associated antigen." (PMID 38304429, 2024). "Although ABO blood group was reported to be associated with several types of cancers, the underline biological mechanism remains unclear." (PMID 36415180, 2023). "In addition to the physiological changes, the association between ABO BG antigens expression and erythropoiesis is known for carcinomas and hematological malignancies." (PMID 36854778, 2023). "Our study also identifies the higher risk of VTE as a result of a multiplicative interaction between rs8176719 (ABO) and cancer, and the risk was higher for the Roma population (β = 0.370, p < 0.001) than for the general Hungarian population (β = −0.042, p = 0.6)." (PMID 34765649, 2021). "Human ABO blood groups are determined by the alleles A, B, and O (O01 and O02) of the ABO gene and have been linked to the risks for cardiovascular diseases and cancers that affect lifespan." (PMID 33103040, 2020). "We also excluded that the decreased representation of blood group antigens expressed by mature erythrocytes could be ascribed to skewing in NB susceptibility depending on ABO system, as observed in other type of cancers." (PMID 28881804, 2017). "Although the associations of the ABO blood type with cancer risk and survival have been reported in several malignancies, the genetic or biological mechanisms underlying the associations remain unclear." (PMID 26411553, 2015). "Previous studies suggest a relationship between ABO blood types and the risk of various cancers." (PMID 24516588, 2014).
cancer (continued). "However, two new studies of cancer risk and several studies of cardiocerebrovascluar diseases risk have been reported in recent years and the relationship between SNPs in ABO gene and cancer/cardiocerebrovascular diseases risk was still unclear." (PMID 32093636, 2020). "These included multitrait colocalization at 6 loci with a consistent direction of effect between CAD and cancer (ABO, PGAP3, ANGPTL4, SREBF1, HAUS6, and SYNJ2BP) and 7 with an opposing direction (CDKN1A, RGS19, CALCRL, SF3A3, LAMC1, MYO9B, and MIA3)." (PMID 40874306, 2025). "It is among the first studies that has shown the link between the ABO system and cancer at the gene level." (PMID 39040623, 2024). "It has recently been found that the presence of ABO antigens on the surface of cancer cells, despite their differences from those of normal cells, is nevertheless linked to the ability of these cells to evade an immune response and undergo apoptosis." (PMID 38337488, 2024). "Recent studies have shown the relationship between the ABO blood group type and the survival rate of some cancers." (PMID 37875876, 2023). "We have also shown that the ABO-bgs was an effective predictor of PSM after adjusting for physical and cancer preoperative factors thus demonstrating close association with PCa biology." (PMID 34189707, 2022). "The carbohydrate moieties of the ABO blood groups are genetically inherited, and previous studies have suggested a correlation between ABO blood type and cardiovascular diseases, cancers, and even certain infections such as SARS coronavirus." (PMID 35784998, 2022). "The epithelial tissues of the oral cavity, gastrointestinal tract, lungs, bladder, breast, cervix and prostate contain ABH antigens, but malignant tumours of these tissues lack ABO blood group antigen expression." (PMID 34376742, 2021). "The possibility of VTE risk increment, as a result of a multiplicative interaction between rs8176719 (ABO) and cancer, was identified, which was higher for the Roma population (β = 0.370, p < 0.001) than for the general population (β = −0.042, p = 0.6)." (PMID 34765649, 2021). "The results of the present study were in accordance to several other studies in literature which were performed to investigate expression of ABO antigens in tissue sections of oral precancer and cancer." (PMID 32334486, 2020). "For several decades, a role for ABO blood group antigens in the development of cancer has been suspected, but the results have been inconsistent." (PMID 31777587, 2019). "Previous studies have suggested that the ABO blood group play an important role in the development of various cancers." (PMID 31777605, 2019). "ABO BG are involved in several benign and malignant diseases and the relationship between human BG and cancer is well known." (PMID 29596526, 2018). "For several decades, a role of ABO blood type antigens in the development of cancer has been suspected." (PMID 28880901, 2017). "The findings of this study support a role of genetic traits related to ABO blood type in the development of cancers in the gastrointestinal and urinary tracts." (PMID 28880901, 2017). "Multiple potential mechanisms to support a role for ABO blood type in cancer development and progression have been proposed." (PMID 28448592, 2017). "Most epidemiological studies have suggested a role for ABO blood groups in the development of cancers, especially for exocrine pancreatic cancer." (PMID 28903383, 2017). "The observation that mouse ABO gene encodes a protein with FS activity warrants further exploration of the possibility that blood group ABO gene-encoded transferases may be involved in the biosynthesis of Forssman antigen in human cancer by yet-to-be defined molecular mechanisms." (PMID 28134301, 2017).